AR (androgen receptor)
Diseases named in the same sentence as AR in open-access papers (continued):
Sharing a sentence is not in itself a finding about the gene and the disease.
neuromuscular disease (23 papers, 2010 to 2025). "Spinal and bulbar muscular atrophy (SBMA) is an adult-onset, X-linked, progressive neuromuscular disease caused by abnormal CAG trinucleotide expansion in the androgen receptor gene, affecting males only." (PMID 40559319, 2025). "Spinal and bulbar muscular atrophy (SBMA) is an X-linked, neuromuscular disease caused by a polyglutamine (polyQ) repeat expansion in the androgen receptor (AR)." (PMID 38452174, 2024). "SBMA is an adult-onset, slowly progressive neuromuscular disease caused by abnormal expansion of the CAG repeat (polyglutamine tract) in the androgen receptor (AR) gene." (PMID 37231024, 2023). "The androgen receptor (AR), an important nuclear hormone receptor that plays a causative role in the neuromuscular disease spinal and bulbar muscular atrophy (SBMA), is regulated by the UPS for both its transcriptional functions and its degradation." (PMID 36277484, 2022). "Kennedy’s disease (KD), also known as spinal and bulbar muscular atrophy (SBMA), is a rare, adult-onset, X-linked recessive neuromuscular disease caused by CAG expansions in exon 1 of the androgen receptor gene (AR)." (PMID 32276665, 2020). "Spinal and bulbar muscular atrophy is a neuromuscular disease caused by an expanded CAG repeat in the androgen receptor gene." (PMID 31537808, 2019). "Spinal and bulbar muscular atrophy (SBMA) is a neuromuscular disease caused by polyglutamine (polyQ) expansion in the androgen receptor (AR)." (PMID 30644418, 2019). "Spinal and bulbar muscular atrophy (SBMA) is a polyglutamine‐mediated neuromuscular disease caused by a CAG repeat expansion in the androgen receptor (AR) gene." (PMID 30940675, 2019). "Spinal and bulbar muscular atrophy (SBMA) is a neuromuscular disease caused by a polyglutamine (polyQ) expansion in the androgen receptor (AR)." (PMID 31686397, 2019). "Spinal and bulbar muscular atrophy (SBMA) is a neuromuscular disease caused by an expanded CAG repeat in the androgen receptor (AR) gene." (PMID 31537808, 2019). "Here we used a transgenic mouse model for spinal and bulbar muscular atrophy (SBMA), a neuromuscular disease caused by polyglutamine expansion in the androgen receptor (AR), to test gene silencing by a newly identified AR-targeting miRNA, miR-298." (PMID 30148479, 2018). "Spinal and bulbar muscular atrophy (SBMA) is a neuromuscular disease caused by the expansion of a polyglutamine tract in the androgen receptor (AR)." (PMID 26971100, 2016). "Spinal and bulbar muscular atrophy (SBMA) is a progressive neuromuscular disease caused by polyglutamine expansion in the androgen receptor (AR) protein." (PMID 26308581, 2015). "Spinal and bulbar muscular atrophy (SBMA), a neuromuscular disease that shares several clinical features with ALS, is caused by CAG trinucleotide repeat expansions (>38 copies) in the androgen receptor (AR) gene." (PMID 35599735, 2022). "Polyglutamine expansion in the androgen receptor (AR) causes spinal and bulbar muscular atrophy (SBMA), an X-linked neuromuscular disease that is fully manifest only in males." (PMID 27312068, 2016). "This possibility was highlighted when the transgenic AR100 YAC mice were crossed with AR null testicular feminization mice (Tfm), as the AR100Tfm mice exhibited an accelerated neuromuscular disease phenotype relative to the AR100 mice." (PMID 23720649, 2013). "Addressing these questions may provide fundamental knowledge onto the physiological role of AR in muscle and may lead to development of novel intervention for this yet incurable and untreatable neuromuscular disease." (PMID 32019272, 2020).
cardiovascular disease (18 papers, 2011 to 2026). "From a diagnostic standpoint, determining the degree of AR expression or activity in cardiovascular tissues aids in determining the severity and course of cardiovascular disorders." (PMID 40678723, 2025). "While the relationship between the AR/androgens and cardiovascular disease is far from conclusive, the risks associated with androgens and CVD are of real concern regarding the prevention of a cardiac event." (PMID 37571268, 2023). "At the same time, the incidence of cardiovascular disease associated with second-generation AR antagonists is significantly decreased in comparison with other AR inhibitors such as abiraterone (CYP17 inhibitor)." (PMID 35864113, 2022). "It has been speculated that overexertion of AR signaling cascades as a result of SARM abuse can be a risk factor for the development of various cardiovascular diseases." (PMID 37571268, 2023). "These “paradoxes” not only reflect the complexity of AR signaling but also point to new opportunities for precision medicine in cardiovascular diseases." (PMID 40678723, 2025). "Exclusion criteria for cardiovascular disease in landmark trials of androgen receptor axis-targeted agents." (PMID 38357197, 2024). "This age-dependence and contradictory role of AR in cardiovascular disease is reflected in our survival data in AR genetic models." (PMID 33927243, 2021). "Additionally, side effects such as seizure and cardiovascular disease have limited the clinical benefits of second-generation AR antagonists." (PMID 35864113, 2022). "The risk of cardiovascular disease is higher in males than females, which could indicate a negative impact of AR signalling." (PMID 33927243, 2021).
metabolic disorders (15 papers, 2012 to 2025). "Even so, a study still illustrated that a high-fat diet induced gut microbiota alteration (increased Lactobacillus and Turicibacter) in castrated mice and male androgen receptor knockout mice, causing metabolic disorder." (PMID 34179063, 2021). "Previous studies have demonstrated that androgen/AR signaling is involved in regulating metabolic homeostasis and the men with lower testosterone level in serum are predispose to metabolic disorders." (PMID 33634140, 2021). "Impaired AR signaling can be responsible for an increased risk of metabolic diseases." (PMID 34867780, 2021). "As a competitive inhibitor of AR, flutamide exhibited therapeutic effect on reproductive and metabolic disorders in PCOS." (PMID 35237237, 2022).
neurological diseases (12 papers, 2011 to 2025). "Alterations in AR have also been associated to neurological diseases, from developmental deficiencies to neurodegenerative disorders." (PMID 36880517, 2023). "Pathways involved in odour detection may be directly linked to emotional mood and memory formation, and AR and testosterone have strong effects on our circadian rhythm and daylength discrimination, which are known risk factors for neurological diseases such as Alzheimer’s." (PMID 38750183, 2024). "Likewise, sex differences appear in testosterone expression, as well as in the expression of the androgen receptor, which may contribute to mental or neurological disorders with sex-specific prevalence rates." (PMID 37892639, 2023). "However, the effects of polyQ length variations within the normal range on the function of AR and impact on the development of the non-neurological disease have not been exactly explained." (PMID 30713477, 2018).
genetic disorders (11 papers, 2020 to 2026). "Owing to the sophistication of case-level data, the HL-specific guidelines have more explicitly classified AR variants toward “likely pathogenic” or “pathogenic”, serving as potential references for other recessive genetic diseases." (PMID 35864128, 2022). "Androgen insensitive syndrome (AIS) is a rare genetic disease resulting from androgen receptor (AR) mutations and one of the causes of 46, XY disorder of sexual development (DSD)." (PMID 33750429, 2021). "All parents were first-degree cousins, highlighting the impact of consanguineous marriage on the increased rate of AR genetic disorders reported in our country." (PMID 38153683, 2024). "This study, by linking disease phenotypes to changes in AR stability, demonstrates the importance of protein stability in the pathogenesis of hereditary disease." (PMID 32694570, 2020).
heart disease (9 papers, 2006 to 2024). "While the roles of estrogen receptors in cardiac disease are well-studied in animals and humans, respective research on androgen receptors (AR) is limited." (PMID 37998524, 2023). "AR compounds are also effective in the treatment of heart diseases." (PMID 39215362, 2024). "However, due to the complexity of the mechanism of AR related active substances in treating heart disease, further pharmacological research is still needed." (PMID 39215362, 2024). "Here we investigate AR protein and mRNA expression in human myocardium of various cardiac diseases." (PMID 37998524, 2023). "In this study, we assess AR protein expression in various cardiac diseases using western blotting." (PMID 37998524, 2023).
endocrine disorders (7 papers, 2014 to 2024). "AIS is a rare endocrine disorder falling within the category of 46,XY DSD caused by mutations within the AR gene located on the X chromosome long arm and is classified as CAIS, PAIS, or MAIS." (PMID 34867780, 2021). "Immune cell populations from both the innate and adaptive immune systems express the androgen receptor (AR) and may therefore be sensitive to fluctuations in androgen bioavailability, which may change with age, sex and as a result of endocrine disorders." (PMID 38579776, 2024). "Expression of the androgen receptor is key to the response of cells and tissues to androgenic steroids, such as testosterone or dihydrotestosterone, as well as impacting the benefit of hormone-dependent therapies for endocrine diseases and hormone-dependent cancers." (PMID 39088439, 2024).
kidney diseases (6 papers, 2006 to 2025). "AD variants were most common in CAKUT, and AR variants in the other genetic kidney diseases." (PMID 40303230, 2025). "Such sex-specificity in renal disease progression is secondary to differences in the levels of gonadal hormones that control androgen receptor mediated control of sexually dimorphic gene expression in tubule segments." (PMID 41474822, 2025). "We identified six genes enriched to kidney diseases and ccRCC (AR, DPP6, GNB3, IL4, SAA1, SEMA3G)." (PMID 35565241, 2022).
neurodevelopmental disorder (5 papers, 2017 to 2025). A behavioral and cognitive disorder with onset during the developmental period that involves impaired or aberrant development of intellectual, motor, or social functions. "Zinc Finger MIZ-Type Containing 1, or ZMIZ1, is a transcriptional co-activator known to interact with the androgen receptor, and its nucleotide variants have been associated with neurodevelopmental disorders." (PMID 33940396, 2021). "Therefore, the interplay between AHR and the androgen receptor (AR), which is linked to dysfunction of the serotonergic system, could contribute to the onset of neurodevelopmental disorders such as ASD." (PMID 39812050, 2025).
gynecologic tumors (4 papers, 2015 to 2024). "Upstream regulator pathway analysis in tumors from AA patients compared with EA patients showed decreased signaling in progestin-associated targets such as AR, the androgen receptor, consistent with the hormonally responsive breast and gynecologic tumors included in this cohort." (PMID 35992327, 2022). "Of interest, breast and gynecologic tumors also have high rates of AR positivity." (PMID 25595907, 2015).
hematological malignancies (4 papers, 2018 to 2024). "A-485 was developed as a selective catalytic p300/CBP inhibitor, which has demonstrated inhibitory effects in several hematological malignancies and androgen receptor-positive prostate cancer." (PMID 32366905, 2020).
inflammation (4 papers, 2017 to 2026). Aberrant reaction of the microcirculation characterized by movement of fluid and leukocytes from the blood into extravascular tissues. "Based on these findings, we next determined if AR signaling in CD4+ T cells attenuated HDM-induced airway inflammation and modified expression of metabolites in CD4+ T cells." (PMID 39404231, 2024). "Further, these findings show that glutaminolysis in Th2 and Th17 cells is required for maximal HDM-induced airway inflammation, providing an in vivo mechanism for how AR signaling attenuates HDM-induced airway inflammation." (PMID 39404231, 2024). "Androgens and AR signaling decrease airway inflammation by reducing alarmin production, resulting in less type 2 inflammation, as well as directly reducing Th17 cell differentiation and neutrophil‐induced airway inflammation." (PMID 41508394, 2026).
reproductive system disease (4 papers, 2010 to 2024). "Identification of the number of AR CAG repeats can be an effective tool to assess the risk of male subfertility and the control of androgen hormone therapy of reproductive diseases." (PMID 36142533, 2022).
hematological cancers (3 papers, 2024 to 2025). "As expected, hematologic cancers harboring activating NSD2 mutations emerged as the most sensitive to treatment with LLC0150 (IC50 ranging from 0.274 - 69.68 nM), which was immediately followed by AR-positive PCa cell lines (shown in red)." (PMID 39251788, 2024).
myopathy (3 papers, 2010 to 2025). A disease of the muscle in which the muscle fibers do not function properly. "Selective androgen receptor modulators (SARMs) are important hypertrophic molecules that are potential treatments for many types of myopathy and osteopathy." (PMID 40680216, 2025). "Additional circumstantial evidence includes the presence of myopathy and transcriptional alterations in polyQ expanded AR mutant mice, and studies of human pathology." (PMID 20886071, 2010).
respiratory disease (3 papers, 2015 to 2025). "Due to the focus of the present study on respiratory disease models, activity of the enzyme was then tested in the mouse lung; however this procedure was unsuccessful as the AR/HRP assay available did not provide enough sensitivity." (PMID 25889951, 2015).
digestive system neoplasm (2 papers, 2020 to 2021). A neoplasm (disease) that involves the digestive system. "Interestingly, a high correlation was observed among AR, ESR1, and PGR genes in gastrointestinal tumors (COAD, READ, and STAD) as they may play a synergistic role in these tumors." (PMID 32536040, 2020).
gynecological diseases (2 papers, 2013 to 2023). "At present, most studies on the influence of testosterone on gynecological diseases focus on androgen receptor (AR) and androgen metabolic pathway." (PMID 38075074, 2023). "The presence of ER alpha, AR, and the orphan G protein-coupled receptor 30 (GPR30) was demonstrated by immunofluorescence in ovaries obtained from 79 pre and postmenopausal patients, undergoing histero-salpingo-oophorectomy for proliferative gynecological diseases." (PMID 24279585, 2013).
infectious disease (2 papers, 2015 to 2017). A disorder directly resulting from the presence and activity of a microbial, viral, or parasitic agent in humans. "Here, for the first time, we demonstrated that this counterpart of the AR could be involved in infectious disease." (PMID 28957431, 2017). "In the future, the same technique could be applied to quickly and accurately determine AR gene content in a newly-sequenced bacterial strain—an application with relevance to infectious disease management." (PMID 26682918, 2015).
retinopathy (2 papers, 2017 to 2025). "Group 2 consisted of 16 German Spitz dogs (6 females, 10 males) affected by early-onset retinopathy caused by the AR variant in the GUCY2D gene, with ages ranging from 1.5 to 22 months (mean ± standard deviation = 5.2 ± 5.4 months)." (PMID 41012804, 2025).
movement disorder (1 paper, 2021). Neurological conditions resulting in abnormal voluntary or involuntary movement, which may impact the speed, fluency, quality and ease of movement. "Complex EOPD forms with rapid progression, early cognitive deterioration, and additional movement disorders instead are usually related to new AR genes." (PMID 34630269, 2021).
psychiatric disorder (1 paper, 2024). A disorder characterized by behavioral and/or psychological abnormalities, often accompanied by physical symptoms. "While this gene’s expression was female-biased across 26 GTEx tissues, perturbing AR is associated with both male- and female-biased adverse events related to psychiatric disorders and nervous system adverse events, respectively." (PMID 38167211, 2024).
skin disorder (1 paper, 2025). Any deviation from the normal structure or function of the skin or subcutaneous tissue that is manifested by a characteristic set of symptoms and signs. "Entities related to skin disorders, which occur frequently in patients taking AR signal transduction inhibitors, appeared infrequently in the top 20 entities." (PMID 40068144, 2025). "“Skin disorder” was more frequently reported as a symptom for AR signaling inhibitors, whereas it was less commonly reported for abiraterone acetate, an androgen synthesis inhibitor." (PMID 40068144, 2025). "Among the positive symptom tags, characteristic entities for AR signal transduction inhibitors such as “skin disorders” and “fatigue” were frequently noted." (PMID 40068144, 2025).
AR also shares sentences with these, for which no sentence is quoted: dentatorubral-pallidoluysian atrophy (8 papers); fragile X syndrome (8); myocardial infarction (8); chronic lymphocytic leukaemia (5); pancreatic adenocarcinoma (5); spinocerebellar ataxia type 1 (5); chronic obstructive pulmonary disease (4); Impotence (4); oral squamous cell carcinoma (4); autism spectrum disorder (3); bacterial infections (3); benign tumors (3); central precocious puberty (3); cutaneous T-cell lymphoma (3); cystic fibrosis (3); gastric adenocarcinoma (3); hepatitis C (3); hepatocellular adenoma (3); hypopituitarism (3); immune disorders (3); non-alcoholic steatohepatitis (3); spinocerebellar ataxia type 7 (3); Turner syndrome (3); acute lymphoblastic leukemia (2); acute respiratory distress syndrome (2); adenocarcinoma of ovary (2); adrenocortical carcinoma (2); alveolar rhabdomyosarcoma (2); amenorrhea (2); angiomas (2).
A further 282 diseases each share a sentence with AR in 2 papers or fewer.